ATM (ATM serine/threonine kinase)
Diseases named in the same sentence as ATM in open-access papers (continued):
Sharing a sentence is not in itself a finding about the gene and the disease.
breast cancer (continued). "Among breast cancer patients the most prevalent occur in BRCA2, CHEK2, BRCA1 and ATM." (PMID 37790698, 2023). "While early age at diagnosis was strongly associated with BRCA1 and modestly with BRCA2, it was associated with only a very modestly (ATM and CHEK2) or no (PALB2) increased risk of carrying a PV in non-BRCA1/2 breast cancer-associated genes." (PMID 37084156, 2023). "We further explore the resistance of mammospheres derived from breast cancer cell lines against DOX chemotherapy and the therapeutic benefit of ATM inhibition upon administration of the water insoluble ATM kinase inhibitor KU, encapsulated in the PTPP nanocarrier (PTPP–KU)." (PMID 36900267, 2023). "Indeed, we have previously demonstrated that ATM is required for DNA damage-induced activation of p65/p50 in breast cancer cells, and in CLL cells ATM interacts with the TCL1 oncogene to activate NF-κB." (PMID 37835430, 2023). "Unlike mutations in ATM or CHEK2, mutations in ATR alone are uncommon in both primary and metastatic ER+/HER2− breast cancer." (PMID 37390209, 2023). "Moreover, next-generation sequencing revealed that beyond BRCA1/2, mutations in homologous recombination effectors, such as PALB2, RAD51, ATM, BRIP1, BARD1, and CHEK2 also occur in breast cancer." (PMID 36613148, 2023). "Increased proportions of cluster 5 indicated that breast cancer activated the non-classical inflammatory ATM phenotype involved in lipid metabolism." (PMID 37153595, 2023). "Among cell cycle checkpoint kinase genes, we observed 1.5-fold enrichment for ATM mutation (alone, not in combination with any other gene of interest) in primary ER+/HER2− breast cancer relative to metastatic disease (P = 0.003)." (PMID 37390209, 2023). "Hence, this study aimed to evaluate the radiosensitizing ability under fractionation of ATM inhibitor AZD0156, ATR inhibitor AZD6738 and PARP inhibitor AZD2281 (olaparib), utilizing MDA-MB-231 and MCF-7 human breast cancer cells." (PMID 35954456, 2022). "A total of 3.6% of patients carried a pathogenic/likely pathogenic variant in a known breast cancer susceptibility gene: 1.2% in BRCA1, 0.6% in each of BRCA2, ATM, CHEK2 and PALB, none of whom had any family history of breast cancer." (PMID 35039564, 2022). "Breast cancer 1 (BRCA1) and breast cancer 2 (BRCA2) play an important role in the HR repair pathway by interacting with other DNA repair proteins such as Fanconi anemia (FA) proteins, ATM, RAD51, PALB2, MRE11A, RAD50, and NBN." (PMID 35785170, 2022). "Our knockdown experiments suggest that the ATM/CHK2 axis is likely necessary for mediating BQ expression in TAM-resistant breast cancer cells, whilst that of ATR and CHK1 is not." (PMID 36293165, 2022). "The results of ‘Egger’s test showed no publication bias in the pooled prevalence of ATM in patients with breast cancer (coefficient = 0.098, P = 0.98)." (PMID 34493284, 2021). "In breast cancer cells, ZEB1 promotes radioprotection by driving the expression of the apical DDR kinase ATM via complex formation with p300 and PCAF at the ATM promoter as well as by stabilizing the mediator kinase CHK1 via sequestration of its deubiquitinase USP7." (PMID 34459003, 2021).
breast cancer (continued). "Breast cancer patients with pathogenic mutations (such as BRCA1/2, CHECK, PALB and ATM) are more prone to have false negative axillary US examinations compared to high-risk breast cancer patients without genetic changes." (PMID 34945851, 2021). "They suggested that the following words be added: autosomal dominant inheritance, HER 2 positive, mammography, MRI, physician assistant, preventive examination, specialized nurse, receptor, sentinel lymph node, triple negative tumor, other breast cancer genes (like CHEK2, PALPB2, and ATM)." (PMID 33001269, 2021). "Further analysis demonstrated that the expression of cell cycle-related genes (CDC6, CDC25A, CDK1, ATM, E2F1, and MKI67) were much higher in breast cancer patients of 3 target genes high expression group or MIR3613 deletion group compared with their counterpart, respectively." (PMID 33494814, 2021). "BRCA1 and BRCA2 germline pathogenic variants were found in 7.3% of the IBC patients, 6.3% had a mutation in other cancer genes (PALB2, CHEK2, ATM and BARD1), and 1.6% had a germline pathogenic variant in other genes not related with breast cancer." (PMID 32075053, 2020). "Although MYC amplification promotes aggressive breast cancer phenotype, whether ATR and ATM expressions influence pathology and clinical outcomes in MYC overexpressed breast cancers is unknown." (PMID 30746633, 2019). "Our cohort study does not support an impact of ATM rs1801516 on radiation-induced late skin injuries in breast cancer patients." (PMID 31756226, 2019). "We conclude that ATR/ATM-directed stratification and personalisation of therapy may be feasible in MYC overexpressed breast cancer." (PMID 30746633, 2019). "Whether ATM and ATR expressions influence clinical outcomes in MYC overexpressed breast cancers is unknown." (PMID 30746633, 2019). "In HepG2, top CPs were “hereditary breast cancer signaling”, “NRF2- mediated oxidative stress response”, “role of BRCA1 in DNA damage response”, “ATM signaling”, “cell cycle control of chromosomal replication”, “estrogen mediated S-phase entry” and “GADD45 signaling”." (PMID 30042885, 2018). "First, ATM phosphorylation was induced by irradiation in breast cancer cells in presence or absence of the ATM inhibitor KU-55933." (PMID 29615613, 2018). "A second female sibling of this patient had inherited the ATM frameshift but not the BRCA2 K3326* variant, and developed breast cancer at the age of 46." (PMID 28591191, 2017). "Finally, tumor array analyses, performed using public data, identify a significant correlation between ATM and ATG4C expression levels in all human breast cancer subtypes, except for the basal-like one." (PMID 28423511, 2017). "It has been demonstrated that the aberrant overexpression of miR-421 may down-regulated ATM, therefore, can lead to SKX squamous cell carcinoma.In addition, it has been shown that miR-203 may be responsible for ATM down-regulation in breast cancers." (PMID 29156695, 2017).
breast cancer (continued). "Carriers of deleterious variants in either ATM, CHEK2, PALB2 or NBN are typically counseled for their risk of breast cancer, but not ovarian cancer risk despite associations in current literature." (PMID 28591191, 2017). "UA induced DNA damage in breast cancer cells and this was accompanied by phosphorylation of ATM but not by phosphorylation of H2AX and 53BP foci formation (this study)." (PMID 28213701, 2017). "To further evaluate the clinical significance of our findings, we asked whether we could identify a significant correlation between ATM and ATG4C expression in breast cancer human samples." (PMID 28423511, 2017). "We and others have reported that the breast cancer risk fraction contributed by missense variants in BRCA1, BRCA2, ATM and CHEK2 is as high, if not higher, than protein-truncating variants in these genes." (PMID 27099641, 2016). "The moderate-risk genes—CHEK2, ATM, and PALB2—had positive yields of 2.0% (n = 66), 1.0% (n = 33), and 0.8% (n = 25), respectively, among the 3,315 women with breast cancer and no previous testing." (PMID 26681312, 2016). "No ATM carriers were found in sporadic ovarian cancer (0/49), non-small cell lung cancer (0/150), colorectal cancer (0/80), and post-menopausal breast cancer (0/58)." (PMID 27599564, 2016). "This was not considered appropriate for the associations with breast cancer risk of PALB2 c.1592delT, c.3113G>A and ATM c.7271T>G because these associations had previously been reported; our aim was to more precisely estimate the associated relative risks." (PMID 27595995, 2016). "Similar to the present study, hypoxia treatment increasing ATM phosphorylation without apparent DNA damage was demonstrated to promote breast cancer metastasis via NF-κB pathway." (PMID 26528698, 2015). "To further assess whether DDR is induced in HMECs by exosomes from all 3 breast cancer cells, we performed IFA to detect γH2AX specific micronuclei formation and phospho ATM in HMECs incubated with exosomes for up to 24 h." (PMID 24831807, 2014). "Indeed, ATM mRNA was lower in MCF10A-1 and in several other SATB1-responsive breast cancer cell lines as compared to MCF10A-2 cells, suggesting that the level of ATM negatively correlates with the responsiveness to SATB1 overexpression." (PMID 23251624, 2012). "In an initial study we used the ATM inhibitor KU-55933 and showed significantly decreased radiation resistance of the CD44+/CD24− subset isolated both from of the MDA-MB-231 cell line and the primary culture of patient breast cancer cells." (PMID 21935375, 2011). "A total of 12 members of this cohort had been treated for breast cancer and 4 of this 12 had levels of the ATM protein < 55% compared with the mean for non-reactor controls." (PMID 20678261, 2010). "We found that 4/12 (33%) of the breast cancer patients with severe adverse normal tissue reactions following radiotherapy had ATM protein levels < 55% compared to the mean for non-reactor controls." (PMID 20678261, 2010). "The radiosensitive breast cancer patients in our cohort expressed a much wider range of ATM protein levels compared with the non-reactor control group." (PMID 20678261, 2010).
breast cancer (continued). "The 4 'low ATM expressers' described here with breast cancer did not recur within the 2-5 year period following radiotherapy." (PMID 20678261, 2010). "Next we investigated whether DCQ causes cell death in human colon cancer cells by inducing DNA damage and activating ATM, as similar effects have been observed in EMT6 mouse mammary carcinoma cell lines." (PMID 21078189, 2010). "Studies in mice have shown that ATM haploinsufficiency is followed by an increased sensitivity to low doses of radiation, carcinogens and an increased incidence of mammary tumours but not increased radiation mutagenesis." (PMID 17623063, 2007). "Our results indicate that common variants in the ATM, CHEK2 or ERBB2 genes are not involved in modifying breast cancer survival or the risk of tumour-characteristic-defined breast cancer." (PMID 17132159, 2006). "Our data did not support an association between common variation in the ATM, CHEK2 and ERBB2 genes and breast cancer survival or the risk of developing tumours of different characteristics." (PMID 17132159, 2006). "For ATM, MRE11A and XRCC4 we repeated the analysis in cases and controls separately to determine whether LD structure was consistent across breast cancer cases and controls." (PMID 16091150, 2005). "There are limited prospective data on whether established risk factors modify breast cancer risk in women with pathogenic variants (PV) in BRCA1/2 and virtually no risk modification data for ATM, CHEK2, or PALB2." (PMID 40298171, 2025). "However, since hereditary and sporadic breast and pancreatic cancer cannot be distinguished and because the penetrance is low for breast cancer, neither situation can be satisfied for ATM." (PMID 38854136, 2024). "To date, no studies have been conducted on breast cancer-driven genes such as ATM, PALB2, CHEK2, and XRCC2 reported from the Khyber Pakhtunkhwa region or Pashtun ethnicity and their potential associations with the various clinicopathologic and hormonal characteristics." (PMID 38784039, 2024). "Statistical adjustments for personal history, type and age of family history, and ancestry using a multivariable logistic regression model further support previous findings that age at breast cancer diagnosis is not a strong predictor of carrying ATM, CHEK2, or PALB2 PVs." (PMID 37084156, 2023). "Conversely, mutations in ATM do not affect age at diagnosis: Patients with germline or somatic ATM mutations remain postmenopausal with median ages of 61 and 54 years, respectively, as expected for patients with ER+/HER2− breast cancer." (PMID 37390209, 2023). "However, familial breast cancer was not as strong of a predictor of ATM or CHEK2 PV status among unaffected women." (PMID 37084156, 2023). "In addition, the last V5 version of BOADICEA incorporates the effects of pathogenic variants (PVs), not only in BRCA1 and BRCA2 genes, but also in PALB2, CHEK2, ATM and BARD1 for the breast cancer model and RAD51D, RAD51C and BRIP1 for the ovarian cancer model." (PMID 35886069, 2022). "One of the individuals with an ATM PGV did not have a family history of breast cancer." (PMID 33763779, 2022). "Moreover, the negative correlation between Notch1 and ATM activation has been observed in human breast cancer, and it contributes to the survival of Notch1 driven leukemia cells upon DNA damage." (PMID 33968932, 2021). "The treatment of breast cancer cell lines (MCF7 and SkBr3) and colon cancer cell line (HCT-116) with the IC50 and twice the IC50 of SIMR1281 for 24 h increased the level of γ-H2Ax and p-ATM, while a minimal effect was detected in the phosphorylation level of ATR." (PMID 34200264, 2021).
breast cancer (continued). "In addition, 158 women with TNBC were recruited for analysis among Polish women, one of whom carried an ATM mutation, while no ATM mutation was detected in 44 women with non-TNBC hereditary breast cancer." (PMID 34198652, 2021). "In this work, we performed an in silico analysis of transcriptomic datasets in breast cancer, and focused on those involved in DNA damage, as were clearly upregulated using gene set enrichment analyses (GSEA), particular the following pathways: ATM/ATR, BARD1 and Fanconi Anemia." (PMID 33925616, 2021). "Hence, our data demonstrate that TAIII triggers DNA damage and activates ATM/Chk2 and p38 MAPK pathways, and then induces G2/M phase arrest and apoptosis in breast cancer, which provide theoretical evidence for TAIII utilized as drug against breast cancer." (PMID 33628174, 2020). "Fisher exact tests with just the 539 breast cancer patients (excluding 29 ovarian cancer patients) yielded almost similar results, except for ATM, which was no longer significant (OR = 11.3, 10.8, 3.8, and 2.4, respectively; p < 0.01, p < 0.01, p = 0.03, and p = 0.07, respectively)." (PMID 32566746, 2020). "As an example, ATM 7271T > G has been considered a rare event in familial breast cancer, whereas ATM IVS10-6T > G mutation did not confer a significantly increased risk of breast cancer." (PMID 32858941, 2020). "TAIII-activated the ATM/Chk2 pathway and the γH2AX are specifically response to the repair of DSBs, so we speculate that the type of DNA damage induced by TAIII in breast cancer cells is DSBs." (PMID 33628174, 2020). "Taken together with our observations that ZEB1 overexpression decreases breast cancer cell sensitivity to EPI and ETOP treatment in an ATM-dependent fashion, ATM upregulation may at least partially account for the resistance of this subset of breast cancers against chemotherapy." (PMID 29352223, 2018). "Indeed, our results suggest that ATM targeting severely impinges not only on the DDR, as previously reported, but also on autophagy functionality, which is required for the homeostasis of the specific subset of breast cancer cells." (PMID 28423511, 2017). "Interestingly, the distribution of BRCA1, BRCA2 and ATM rare germline truncations with their somatic mutations across cancer types varies with the high frequency of ATM in prostate, lung and stomach cancers, and BRCA1 and BRCA2 germline events in ovarian and breast cancers." (PMID 26689913, 2015). "Indeed, other data do not support the suppressor role of ATM as no defective expression of ATM has been observed in sporadic breast cancers." (PMID 25247188, 2014). "Application of an ATM inhibitor effectively decreased the radiation resistance of CD44+/CD24−or low subset, suggesting that targeting ATM signaling may provide a new tool to eradicate stem-like CIC and abolish the radiation resistance of breast cancer." (PMID 21935375, 2011). "As expected, a clonogenic assay showed that the overexpression of miR-18a resulted in rendering both MDA-MB-231 and SKBR3 breast cancer cell lines significantly hypersensitive to IR, but further ectopic expression of miR-18a in ATM-depleted cells did not increase sensitivity to IR." (PMID 21980462, 2011). "Overexpression of miR-18a in both MDA-MB-231 and SKBR3 breast cancer cell lines drastically suppressed the GFP protein expression, but not the expression of GFP-γ-tubulin that was used as the transfection control, suggesting that miR-18a specifically affected the ATM-3′-UTR." (PMID 21980462, 2011).